ZNF355P (zinc finger protein 355, pseudogene)
Description:
May be involved in transcriptional regulation.
Synonyms: PRED65; formerly ZNF834
Gene: Unprocessed pseudogene on chromosome 21 (13,095,305 to 13,113,790, reverse strand). Ensembl gene ENSG00000168122.
Subcellular location: Nucleus